LATS1 (large tumor suppressor kinase 1)
Diseases named in the same sentence as LATS1 in open-access papers (continued):
Sharing a sentence is not in itself a finding about the gene and the disease.
bladder cancer (4 papers, 2014 to 2025). "For further verification, by transfecting wild-type or mutant LATS1 plasmids into 293T or bladder cancer cells and confirmed that mutation of SBC1 led to remarkable blockade of LATS1 degradation mediated by SPOP, while depletion of SBC2 had little effect." (PMID 37684641, 2023). "To assess if the various SNPs/variants alter the expression of the LATS1 gene, we examined the RNA steady state levels of LATS1 in the different urinary bladder cancer tissues utilized in this study." (PMID 25628642, 2014). "The differential expression of the LATS1 mRNA in the urinary bladder cancer tissues that shared LATS1 SNPs/variants urged us to assess potential roles for SNPs/variants in the non-coding regions of LATS1 on its expression." (PMID 25628642, 2014). "The effect of this variant could have contributed to LATS1 over-expression observed with the urinary bladder cancer tissue (UC13), at which the variant at 42029 was reported." (PMID 25628642, 2014). "Tissue microarrays and clinical samples indicated that LATS1 was aberrantly downregulated in bladder cancer tissues compared with adjacent normal tissues." (PMID 37684641, 2023). "Taken together, these results confirmed that circXRN2 modulated LATS1 protein levels in bladder cancer cells by regulating posttranscriptional ubiquitylation." (PMID 37684641, 2023). "On the other hand, the novel variant at consensus position 41625, located at exon 6 of the LATS1 gene, was only detected in urinary bladder cancer tissues." (PMID 25628642, 2014). "The LATS1 gene was amplified and sequenced and the expression of LATS1 at the RNA level was assessed in 12 urinary bladder cancer samples." (PMID 25628642, 2014). "Therefore, to verify that SPOP was involved in the ubiquitylation and degradation of LATS1 in human bladder cancer cells, we first performed IP followed by mass spectrometric detection with LATS1 antibodies in T24 cells." (PMID 37684641, 2023). "Considering that LATS1 is a key molecule in the kinase cascade of the Hippo pathway, we further demonstrated that circXRN2 activates the Hippo signaling pathway, thereby regulating biological functions in bladder cancer cells." (PMID 37684641, 2023). "First, our study demonstrated that circXRN2 could interact with the LATS1 protein and was dysregulated in bladder cancer cell lines and surgical samples." (PMID 37684641, 2023). "Given the close relationship between circXRN2, LATS1 and the Hippo pathway, we hypothesized that circXRN2 plays a key role in glycolysis in bladder cancer cells." (PMID 37684641, 2023). "LATS1 interacted with the SPOP protein in bladder cancer cells." (PMID 37684641, 2023). "The differential expression of the LATS1 mRNA in the urinary bladder cancer tissues that shared LATS1 SNPs/variants suggested a role for the SNPs/variants (in non-coding regions) in LATS1 expression." (PMID 25628642, 2014). "Here, we discovered, for the first time, that circXRN2 activates the Hippo pathway by stabilizing LATS1, which in turn suppresses H3K18 lactylation-driven tumor progression in human bladder cancer." (PMID 37684641, 2023). "A urinary bladder cancer tissue sample (UC13) showed higher levels of the LATS1 expression compared with peritumoral tissue and urinary bladder cancer tissue without any variation within the LATS1 gene (UC6)." (PMID 25628642, 2014).
clear cell renal cell carcinoma (4 papers, 2018 to 2024). "The aim of the study was to determine by immunohistochemistry cellular localization and immunoreactivity levels of YAP1 and LATS1 proteins in paired sections of tumor and unchanged renal tissues of 54 clear cell renal cell carcinoma (ccRCC) patients." (PMID 29850494, 2018). "In clear cell renal cell carcinoma, RNF43 can inhibit malignant behavior and reverse pazopanib resistance by inhibiting the YAP signaling by decreasing YAP phosphorylation via p-LATS1/2." (PMID 37848933, 2023).
esophageal cancer (4 papers, 2012 to 2025). A primary or metastatic malignant neoplasm involving the esophagus. "Our results showed that the core components of the Hippo pathway (Mst1/2, LATS1, and Mob1) and the RASSF1 protein coimmunoprecipitated and that their binding was significantly enhanced by rhBMP-2 treatment in both esophageal cancer cell lines." (PMID 27230238, 2016).
lymph node metastasis (4 papers, 2015 to 2021). "Decreased expression of LATS1 was associated with the lymph node metastasis (P = 0.012)." (PMID 26921249, 2016). "Consequently, decreased LATS1 expression was significantly associated with the lymph node metastasis, poor prognosis and recurrence." (PMID 26921249, 2016). "Multivariate analysis showed that, in addition to the lymph node metastasis, LATS1 expression might act as an independent prognostic factor for overall survival (OS) (P = 0.017) and recurrence-free survival (RFS) (P = 0.026) of GC patients." (PMID 26921249, 2016). "Moreover, the expression levels of SAV1 and LATS1 in GC patients with lymph node metastasis were significantly lower than those in GC patients without lymph node metastasis." (PMID 26267324, 2015).
malignant mesothelioma (4 papers, 2016 to 2024). A malignant neoplasm of the pleura or peritoneum, arising from mesothelial cells. "A LATS1::PSEN1 gene fusion, which results in loss of function of LATS1 and therefore YAP/TAZ activation, has been detected in a malignant mesothelioma cell line that lacks the second LATS1 allele." (PMID 40491864, 2024).
skin cancer (4 papers, 2022 to 2025). "Arsenic modulates Hippo pathway activity by upregulating key proteins like Large Tumor Suppressor Kinase 1/2 (LATS1), Salvador homologue-1 (Sav1) and ste20-like kinase 1/2 (Mst1), which are known to play roles in various cancers, including skin cancer." (PMID 40680435, 2025).
thyroid cancer (4 papers, 2020 to 2023). "LATS1 binds to LIM kinase (LIMK) 1 and inhibits the activity of LIMK1 to regulate cytokinesis, and LIMK1 was implicated in the pathogenesis of thyroid cancer and ATC." (PMID 35350839, 2022). "Interestingly, miR-1278 is enriched in thyroid cancer, whereby it regulates cell proliferation and invasion by targeting LATS1, suggesting a heterogeneous role of miR-1278 in tumor cells." (PMID 38025524, 2023). "Upregulation of LATS1 through downregulation of miR-103a-3p repressed malignancy of thyroid cancer." (PMID 35350839, 2022).
colitis (3 papers, 2021 to 2023). Inflammation of the colon. "Markedly, attenuated the Hippo signaling by LATS1 deficiency nicely restored the severe colitis phenotypes in PPM1A mice." (PMID 33630828, 2021). "MiR-590-3p, a factor in M2 macrophage-derived exosomes, reduces inflammatory signalling and promotes epithelial regeneration by targeting LATS1 in colitis mice." (PMID 36691021, 2023). "There are four major MIR31 target proteins, Gp130, IL17RA, Axin1, and Lats1/2, with certain probabilities of acting on inflammation and regeneration in colitis." (PMID 36590397, 2022). "To confirm that PPM1A interacts with Hippo signaling genetically, we attempted to examine the colitis phenotypes of Ppm1a−/−/Lats1+/− mice obtained by crossing the PPM1A KO mice with LATS1 heterozygotes." (PMID 33630828, 2021). "Furthermore, a specific inhibitor of MST kinases, or half-deficiency of LATS1, well rescues the defective phenotype in PPM1A KO mice, demonstrating that the key role of the PPM1A-YAP axis in guts and livers and diseases such as colitis." (PMID 33630828, 2021).
endometrial cancer (3 papers, 2020 to 2024). Primary or metastatic malignant neoplasm involving the endometrium (mucous membrane that lines the endometrial cavity). "LATS1/2 are frequently mutated and down-regulated in endometrial cancer (EC), but the contributions of LATS1/2 in EC progression remains unclear." (PMID 38383447, 2024). "In this study, we revealed a new tumor immune evasion mechanism utilized by endometrial cancer (EC) that involves the downregulation of LATS1/2." (PMID 38383447, 2024). "Similarly, ectopically expressed wild-type p190A, but not endometrial cancer-associated p190A mutants, elevated LATS1/YAP phosphorylation and reduced nuclear YAP localization." (PMID 32457342, 2020).
fibrosarcoma (3 papers, 2015 to 2020). A malignant mesenchymal fibroblastic neoplasm affecting the soft tissue and bone. "However, ~14% of surviving female Lats1−/− mice developed large NRSTS by 4–10 months of age consistent with fibrosarcomas." (PMID 26389076, 2015).
leukemia (3 papers, 2009 to 2020). A malignant (clonal) hematologic disorder, involving hematopoietic stem cells and characterized by the presence of primitive or atypical myeloid or lymphoid cells in the bone marrow and the blood. "This suggests the possibility that a reduction in LATS1/2 activity may underlie the alterations in YAP/WWTR1 stabilization and activation in the context of leukemia." (PMID 33061801, 2020).
medulloblastoma (3 papers, 2015 to 2024). A malignant, invasive embryonal neoplasm arising from the cerebellum. "Interestingly, signals through Gαs subunit can activate AC and PKA, thereby phosphorylating the large tumor suppressor 1 and 2 (LATS1/2), which exerts antitumor effects in medulloblastoma and basal cell carcinoma." (PMID 34510318, 2022).
Ovarian cyst (3 papers, 2019 to 2025). The presence of one or more cysts of the ovary. "Deletion of Lats1 results in germ cell loss and formation of ovarian cysts and stromal tumors, while ovarian fragmentation leads to YAP1 upregulation and increased follicular development." (PMID 31883523, 2019). "In vitro studies have found that excessive proliferation of ovarian somatic cells, caused by LATS1 deletion, may cause ovarian cyst formation." (PMID 36009693, 2022). "The ablation of LATS1 in mice causes increased germ cell apoptosis with subsequent primordial follicle loss, development of ovarian cysts and stromal tumors, and lack of mammary glands." (PMID 41393291, 2025).
bladder tumor (2 papers, 2014 to 2023). "That being said, in the present study we observe an association of these SNPs/variants with the differential expression of LATS1 in urinary bladder tumors." (PMID 25628642, 2014). "To confirm that the circXRN2/LATS1 axis regulates various biological functions and glucose metabolism in bladder tumor cells, we knocked down LATS1 protein in cells overexpressing circXRN2." (PMID 37684641, 2023).
chondrosarcoma (2 papers, 2020 to 2024). A malignant cartilaginous matrix-producing mesenchymal neoplasm arising from the bone and soft tissue. "A recent study identified YAP nuclear accumulation as a consequence of LATS1 inactivation by protein arginine methyltransferase 1 (PRMT1) as an independent bad prognostic factor in chondrosarcoma." (PMID 32326412, 2020). "Among epigenetic drugs, only JQ1 was previously reported to affect LATS1, YAP and TAZ in chondrosarcoma, potentially by restoring suppressed AMOT expression." (PMID 32326412, 2020). "Finally, the treatment of chondrosarcoma cells with the BET-bromodomain inhibitor JQ1 downregulated YAP/TAZ and LATS1, leading to the upregulation of cyclin-dependent kinase inhibitor 1a (CDKN1A/p21) and cell cycle arrest, senescence and apoptosis." (PMID 32326412, 2020).
colon adenocarcinoma (2 papers, 2024). "Moreover, USP2-AS1 overexpression decreased the p-LATS1, LATS1, LATS2, and p-YAP1 levels and increased total YAP1 level in colon adenocarcinoma cell lines." (PMID 38226210, 2024).
ependymoma (2 papers, 2020 to 2024). A WHO grade II, slow growing tumor of children and young adults, usually located intraventricularly. "Our study suggests that nlsYAP5SA and LATS1/2 cKO mice are valuable models of YAP1-fusion ependymoma for biological and preclinical research." (PMID 32404936, 2020). "Our results show that nlsYAP5SA and LATS1/2 cKO mouse models are similar to ependymoma in general, in terms of histology, immunoprofile and ultrastructural features." (PMID 32404936, 2020). "Our nlsYAP5SA and LATS1/2 cKO mouse models indicate the notion that YAP/TAZ activity alone is sufficient for ependymoma-like tumour formation." (PMID 32404936, 2020). "Nevertheless, these data support the use of nlsYAP5SA and LATS1/2 cKO mice as ependymoma models." (PMID 32404936, 2020). "Similar to other ependymoma mouse models, in LATS1/2 cKOs we did not observe rosettes or well-formed pseudo-rosettes, which are commonly observed in human ependymomas and are also present in the mEPEphb2 model." (PMID 32404936, 2020).
heart failure (2 papers, 2020 to 2022). Inability of the heart to pump blood at an adequate rate to meet tissue metabolic requirements. "The Hippo pathway may also suppress cardiomyocyte proliferation via the inhibition of Wnt signaling, and previous reports indicate that the inhibition of Hippo signaling may reverse the progression of heart failure in mice, while SAV1 and LATS1/2 inhibition can improve myocardial recovery." (PMID 32730272, 2020).
Insulin resistance (2 papers, 2019 to 2025). Increased resistance towards insulin, that is, diminished effectiveness of insulin in reducing blood glucose levels. "Activation of Hippo signalling by ad‐Lats1 or sh‐YAP ameliorates insulin resistance, hepatic steatosis and hyperlipidaemia in diabetic mice." (PMID 30821074, 2019). "Therapeutic LATS1 overexpression impedes YAP dephosphorylation and nuclear translocation, ameliorating hepatic steatosis and systemic insulin resistance in diabetic models." (PMID 40247356, 2025).
intrahepatic cholangiocarcinoma (2 papers, 2022 to 2025). A carcinoma that arises from the intrahepatic bile duct epithelium in any site of the intrahepatic biliary tree. "Another study has revealed that WWC1 cooperated with NF2 to mitigate the malignant progression of intrahepatic cholangiocarcinoma by activation of LATS1/2 and inhibition of YAP/TAZ activity." (PMID 36158126, 2022).
kidney cancer (2 papers, 2023 to 2024). Primary or metastatic malignant neoplasm involving the kidney. "Depletion of YAP/TAZ in mice with renal tubular-specific Lats1/2 ablation, conversely, attenuated kidney cancer development, revealing the oncogenic role of YAP/TAZ activation in RCC progression." (PMID 39123485, 2024). "A recent study showed that SPOP increases ubiquitination of the LATS1 protein and promotes its degradation in kidney cancer." (PMID 37684641, 2023).
lipodystrophy (2 papers, 2022 to 2024). A congenital or acquired disorder characterized by abnormal loss or redistribution of the adipose tissue in the body. "However, the Lats1/2 deletion causes severe lipodystrophy, which has not been observed during AT development or under pathological conditions." (PMID 36229481, 2022).
malignant pleural mesothelioma (2 papers, 2022 to 2023). A malignant neoplasm that arises from mesothelial cells in the pleura and shows a diffuse growth pattern. "What’s more, it was reported that MLN4924 could inhibit the ubiquitination of Lats1 and 2 mediated by CRL4DCAF1, thereby inducing the phosphorylation and inactivation of YAP which led to the inhibition of proliferation in malignant pleural mesothelioma." (PMID 35685435, 2022).
metastatic prostate carcinoma (2 papers, 2017 to 2022). A carcinoma that arises from the prostate gland and has spread to other anatomic sites. "Increase in the nuclear localization of YAP has been shown in liver and PCa and down-regulation of LATS1/2 expression is observed in metastatic prostate cancer." (PMID 28052036, 2017).
muscular dystrophy (2 papers, 2018 to 2022). Muscular dystrophy (MD) refers to a group of more than 30 genetic diseases characterized by progressive weakness and degeneration of the skeletal muscles that control movement. "Moreover, synergist ablation, muscle injury, and muscular dystrophy all increase the expression of Lats1." (PMID 34984591, 2022). "We demonstrated for the first time that YAP1 expression is decreased and LATS1/2 kinase activity increased in DMD muscles but not in muscles from patients with other types of muscular dystrophy, stressing the specificity of the results." (PMID 30304034, 2018).
myocardial infarction (2 papers, 2020 to 2022). Gross necrosis of the myocardium, as a result of interruption of the blood supply to the area, as in coronary thrombosis. "The protective effects of downregulating circFASTKD1 following myocardial infarction can be explained by our findings that circFASTKD1 sponges miR-106a and thus de-represses LATS1 and LATS2." (PMID 33411690, 2020).
pituitary tumor (2 papers, 2019 to 2022). A benign or malignant neoplasm affecting the pituitary gland. "Lats1, a tumor suppressor homolog, affects the promoter activity of cellular Gh1 and Prl in pituitary tumors, and Lats1 is involved in the regulation of prolactin expression." (PMID 36555554, 2022). "We recently reported enhanced expression of YAP/TAZ in a range of non-functioning human pituitary tumours, compared to functioning adenomas, and that Lats1 knock-down in GH3 pituitary mammosomatotropinoma cells results in repression of the Gh and Prl promoters." (PMID 30912742, 2019).
Renal cyst (2 papers, 2020 to 2025). A fluid filled sac in the kidney. "IHC revealed strong positivity for p‐LATS1 in nphp1KO mice's renal cyst cells, but weak positivity in WT mice." (PMID 39995111, 2025). "Moreover, the Kibra, p‐MST1/2, p‐LATS1 and p‐YAP were more positive in or around the renal cysts." (PMID 39995111, 2025). "Furthermore, we demonstrated that SNX9 interacted directly with YAP and promoted LATS1-mediated YAP phosphorylation, resulting in the cytoplasmic retention of YAP and the transcriptional inactivation of the YAP/TEAD4 complex, which, consequently, retards renal cyst development." (PMID 32974348, 2020).
serous carcinoma (2 papers, 2019 to 2024). "The OncoPrint results showed that all these genes had significantly amplified in high-grade serous carcinoma patients except the LATS1 gene." (PMID 38730733, 2024). "Of note, LATS1/2 expression was significantly higher in grade 3 than grade 2 in the overall cohort: a statement not meaningful for the serous carcinoma sub-cohort, because only one single case was available in the low-grade group." (PMID 31586262, 2019). "Secondly, LATS1/2 expression was not favorable for overall survival in both the overall cohort and the serous carcinoma sub-cohort." (PMID 31586262, 2019). "LATS1/2 expression was not different among the different FIGO stages for both the overall tumor patient cohort and the serous carcinoma sub-cohort." (PMID 31586262, 2019).
serous ovarian cancer (2 papers, 2019 to 2020). "It had been found that the expression level of LATS1 had decreased in serous ovarian cancer patients but this gene highly expressed in normal ovarian tissue." (PMID 32429941, 2020). "Specifically interested in the serous ovarian carcinoma, we then analyzed LATS1/2 expression in this group of patients, which was also the largest histological subtype (n = 52) in our cohort." (PMID 31586262, 2019). "The TCGA-RNASeqV2 data set showed that low LATS1 and LATS2 were associated with better survival in serous ovarian carcinoma." (PMID 31586262, 2019).
squamous cell carcinoma (2 papers, 2016 to 2025). A carcinoma arising from squamous epithelial cells. "In the first step, we measured YAP, LATS1/2, JNK1/2, ABL1 and MAP4K4 gene expression in the A431 cell line to identify which disturbances in the Hippo pathway and their regulators are present in the standardized squamous cell carcinoma cell line." (PMID 40149574, 2025).
adenomyosis (1 paper, 2023). The growth of endometrial tissue inside the muscular wall of the uterine corpus. "The western blot results showed that the expression of Mst1, p-Lats1, and p-YAP was increased, and the expression of YAP, Tead, and Cyr61 was decreased in the verteporfin group compared with the adenomyosis group." (PMID 36940085, 2023).